PROCR (protein C receptor)
Diseases named in the same sentence as PROCR in open-access papers (continued):
Sharing a sentence is not in itself a finding about the gene and the disease.
COVID-19 (15 papers, 2020 to 2025). A disease caused by infection with severe acute respiratory syndrome coronavirus 2. "Plasma from patients with severe or moderate COVID-19 induced significant upregulation of genes encoding tissue factor, E selectin, and Angpt-2 and concurrently decreased the expression of antithrombotic genes encoding endothelial protein C receptor (EPCR), TFPI, and thrombomodulin." (PMID 34506304, 2021). "mRNA levels for regulators of the kallikrein–kinin (C1-inhibitor), coagulation (thrombomodulin, endothelial protein C receptor), and fibrinolytic (urokinase and urokinase receptor) pathways were significantly reduced in COVID-19 patients." (PMID 33683204, 2021). "Pulmonary ECs of COVID-19 patients show increased expression of pro-coagulant vWf and decreased expression of the anticoagulants thrombomodulin (TM) and endothelial protein C receptor (EPCR)." (PMID 37175942, 2023). "In addition, considering that THBD, PROCR, and F2R are also involved in the regulation of the inflammatory response, we suggest another important interface that supports the involvement of APC in the pathogenesis of the COVID-19-associated coagulopathy." (PMID 36560757, 2022). "In addition, some studies have found that the expression of thrombomodulin and protein C receptor on endothelial cells in COVID-19 patients is significantly decreased, and its mechanism is related to the infiltration of immune cells in the lungs of COVID-19 patients." (PMID 36408343, 2022). "The change in transcription of PROC and the activator receptors PROCR, FR2, and THBD in patients with COVID-19 suggests impaired cytoprotection and progression to the hypercoagulable state." (PMID 36560757, 2022).
thrombosis (15 papers, 2012 to 2025). "GWAS data have also implicated PROCR variants in myocardial infarction, deep vein thrombosis, and pregnancy-associated thrombosis, supporting the notion that genetic alterations in EPCR can modulate thrombotic risk." (PMID 40370698, 2025). "Recently, gene polymorphisms in factor XIII (FXIII) and endothelial protein C receptor (EPCR) have also been studied in association with venous thrombosis and RPL." (PMID 33033453, 2020). "Also, in the Turkish and Swedish populations, an association was observed between the rs867186 polymorphism of the PROCR gene and venous thrombosis." (PMID 38392646, 2024). "New association signals from cross-ancestry GWASs included, for example, variants at PROCR, GRK5 and F11 (thrombosis), LPA and ATP2B1 (lipid metabolism, hypertension and atherosclerosis), SWAP70 (membrane ruffling) and LAMC1 (cerebrovascular matrisome)." (PMID 36180795, 2022). "Thrombosis is a serious vascular disorder influenced by genetic factors, including nonsynonymous single nucleotide polymorphisms (nsSNPs) in the PROCR gene, which encodes the endothelial protein C receptor (EPCR)." (PMID 40370698, 2025). "- endothelial protein C receptor (EPCR)-lysobisphosphatidic acid (LBPA) engagement by aPL, leading to thrombosis and driving dendritic cell interferon-α production for the expansion of aPL-secreting B1 cells." (PMID 35299976, 2022).
thrombophilia (12 papers, 2007 to 2025). A condition characterized by an abnormally high level of thrombi. "A reduction in the profibrinolytic effect of activated protein C, induced by PROCR rs867186, in combination with variants that alter the fibrin structure towards an increased lysis resistance and are therefore prothombic might constitute a relevant risk factor for thrombophilia." (PMID 37175682, 2023). "Soluble Endothelial Protein C Receptor (sEPCR) may be a biomarker of a hypercoagulable state." (PMID 23136988, 2012).
endothelial dysfunction (11 papers, 2012 to 2024). In vascular diseases, endothelial dysfunction is a systemic pathological state of the endothelium (the inner lining of blood vessels) and can be broadly defined as an imbalance between vasodilating and vasoconstricting substances produced by (or acting on) the endothelium. "Endothelial dysfunction also impairs the activation of protein C, which depends on the endothelial protein C receptor and thrombomodulin, whose expression is reduced in damaged microvasculature, enhancing hypercoagulability status." (PMID 29694626, 2018).
endotoxemia (7 papers, 2012 to 2024). "The potential role of the endothelial protein C receptor in regulating HPV during endotoxemia warrants further studies." (PMID 31159807, 2019).
venous thromboembolism (7 papers, 2011 to 2025). Occlusion of the lumen of a vein by a thrombus that has migrated from a distal site via the blood stream. "Characteristics of the investigated studies of the association between the endothelial cell protein C receptor (EPCR) gene rs867186 polymorphism and venous thromboembolism (VTE)." (PMID 28603500, 2017). "Our results provide evidence that PROCR and DNAJC6 might play a role in protein C and free protein S plasma levels in the population studied, warranting further investigation on the role of these loci in the etiology of venous thromboembolism and other thrombotic diseases." (PMID 22216198, 2011).
lupus (6 papers, 2020 to 2025). "CD40L-driven DC activation and interferon production contribute to autoimmunity in lupus, where innate immune activation and coagulation crosstalk are amplified by endothelial protein C receptor (EPCR) and tissue factor signaling." (PMID 40333325, 2025).
ovarian carcinoma (6 papers, 2012 to 2020). A malignant neoplasm originating from the surface ovarian epithelium. "In the study reported here, we present data on the significance of soluble endothelial protein C receptor (sEPCR) in circulating immune cells and the regulation of cytokines and interleukins in plasma of patients with ovarian cancer." (PMID 23877403, 2013). "Of the 146 biopsies from ovarian cancer tested before (n=84) and after (n=62) treatment, 90.47 and 56.6% of biopsies were positive for the protein C receptor, respectively." (PMID 22614534, 2012). "In addition, the soluble endothelial protein C receptor (sEPCR) was quantified by ELISA in ascitic fluid of patients with ovarian cancer." (PMID 26082331, 2015). "Indeed, PROCR has a tumor promoting effect and its silencing in gastric cancer inhibits the proliferation and migration via the ERK1/2 pathway, while, in ovarian cancer cells, it induces cell migration via MEK-ERK and Rho-GTPase pathways." (PMID 32526853, 2020).
acute respiratory distress syndrome (5 papers, 2016 to 2022). Progressive and life-threatening pulmonary distress in the absence of an underlying pulmonary condition, usually following major trauma or surgery. "Altered plasma levels of protein C, thrombomodulin, and the endothelial protein C receptor are associated with poor clinical outcomes in patients with acute respiratory distress syndrome (ARDS)." (PMID 27215212, 2016). "Using protein monitoring technology, they learned that the change of endothelial protein C receptor will increase cell adhesion, and the improvement of cell adhesion is the main influencing factor of acute respiratory distress syndrome." (PMID 36299681, 2022).
colorectal cancer (5 papers, 2012 to 2025). A primary or metastatic malignant neoplasm that affects the colon or rectum. "As expected, tumor-derived organoids highly expressed in vivo tumor-specific genes, many of which have been widely reported to be closely related to colorectal cancer progression and metastasis, such as PROCR, SCD, BMP4, CEACAM6, TESC, and TGFBI." (PMID 35484598, 2022). "To evaluate whether CAFs expressing Tr-CAF markers could inhibit tumor progression, we investigated the correlation between the CAF-specific immunohistochemical (IHC) staining levels for these 4 CAF markers; CXCL14, ADAMDEC1, EDNRB, and PROCR, and the clinical outcomes of colorectal cancer patients." (PMID 40759242, 2025).
ischemic stroke (5 papers, 2014 to 2025). A stroke disorder caused by obstruction of blood flow to the brain, due to thrombotic (local blood clot formation) or embolic (due to a blood clot or other material traveling from another site) event. "There was strong evidence for colocalization of genetic associations with soluble PROCR pQTL and ischemic stroke at this locus (posterior probability, 0.99)." (PMID 40188416, 2025). "Association analyses of the EA revealed a significant association of PROCR rs9574 with ischemic stroke, with the rs9574C allele (MAF case/control = 0.49/0.41) associated with a 1.33-fold increased odds of stroke compared to the G allele (p = 0.003)." (PMID 30383853, 2018). "Here we pursue an a priori hypothesis that genetic variation in the endothelial-based receptors of the thrombomodulin−protein C system (THBD and PROCR) may similarly be associated with early-onset ischemic stroke." (PMID 30383853, 2018). "To this end we tested the hypothesis that THBD (OMIM 188040) and PROCR (OMIM 600646) variants are associated with early-onset ischemic stroke using a 2-stage discovery and replication design, and then addressed whether the identified variants also associated with older-onset disease." (PMID 30383853, 2018). "The 6 pQTLs that were associated with ischemic stroke risk (tissue factor pathway inhibitor, HMWK, prothrombin, prekallikrein, factor XI, and soluble PROCR) were all associated with VTE." (PMID 40188416, 2025).
atherosclerosis (4 papers, 2017 to 2025). A disease characterized by the build-up of fatty material and calcium deposition in the arterial wall resulting in partial or complete occlusion of the arterial lumen. "Thrombomodulin (TM) and endothelial protein C receptor (EPCR), key mediators of protein C activation (PC), have vasculoprotective and anti-inflammatory roles, yet their involvement in macrophage efferocytosis in diabetes-induced atherosclerosis remains unclear." (PMID 41083981, 2025).
coagulopathies (4 papers, 2021 to 2022). "Further genetic modifications included transgenic overexpression of human proteins to decrease cellular injury (CD47 and Hemoxygenase 1), complement activation (hCD55 and hCD46) and coagulopathies (human Endothelial Cell Protein C Receptor and human Thrombomodulin)." (PMID 36568986, 2022).
gastric cancer (4 papers, 2017 to 2024). A primary or metastatic malignant neoplasm involving the stomach. "Among the differentially expressed NRGs, PROCR and MAPK3 showed highest copy number loss frequency in stage I and stage II gastric cancer patients." (PMID 38221932, 2024).
inflammatory bowel disease (4 papers, 2020 to 2023). A spectrum of small and large bowel inflammatory diseases of unknown etiology. "Autoantibodies against the protein C receptor were reported for diagnosing inflammatory bowel disease." (PMID 37715022, 2023).
Stroke (4 papers, 2012 to 2018). Sudden impairment of blood flow to a part of the brain due to occlusion or rupture of an artery to the brain. "We sought to replicate the PROCR rs9574 and rs2069951 association in the Early-Onset Stroke Consortium, with exclusion of the GEOS study." (PMID 30383853, 2018). "His report covered the permeability transition in mitochondria and thereby described a second neuroprotective route: the activated protein C / endothelial protein C receptor signaling system, which was shown as a promising target in several stroke models." (PMID 22883324, 2012).
autoimmune disease (3 papers, 2022 to 2024). A disorder resulting from loss of function or tissue destruction of an organ or multiple organs, arising from humoral or cellular immune responses of the individual to their own tissue constituents. "Evidence is mounting that the nature of the lipid bound to the endothelial cell protein C receptor (EPCR) has an impact on its biological roles, as observed in anticoagulation and more recently, in autoimmune disease." (PMID 36068249, 2022).
coronary artery disease (3 papers, 2012 to 2025). "Due to their influence on lipid metabolism and coagulation processes, LPL, PROCR (endothelial cell protein C receptor) and PDGF may affect the atherosclerotic process and, thus, the risk of coronary heart disease." (PMID 38392646, 2024). "The results of our study suggest that the PROCR rs867186 gene polymorphism is not a significant genetic risk factor for unstable angina in our population, but this polymorphism may affect some lipid metabolism parameters in patients with coronary artery disease." (PMID 38392646, 2024).
ischemia (3 papers, 2013 to 2023). A hypoperfusion of the BLOOD through an organ or tissue caused by a PATHOLOGIC CONSTRICTION or obstruction of its BLOOD VESSELS, or an absence of BLOOD CIRCULATION. "Additional new genetics may further improve thromboregulation (e.g., tissue factor pathway inhibitor [TFPI], endothelial protein C receptor [EPCR], CD39) or reduce inflammation (HO-1, TNFRI-Fc, A20, CD39) and ischemia–reperfusion injury (CD39, HO-1)." (PMID 25098626, 2013).
pneumonia (3 papers, 2013 to 2022). An acute, acute and chronic, or chronic inflammation focally or diffusely affecting the lung parenchyma, caused by an infection in one or both of the lungs (by bacteria, viruses, fungi, or mycoplasma.). "However, the influx of endothelial protein C receptor positive neutrophils into lung tissue can cause pneumonia after the infection of SP, because endothelial protein C receptor can impair antibacterial defense in pneumococcal pneumonia." (PMID 28589151, 2017).
ulcerative colitis (3 papers, 2020 to 2025). An inflammatory bowel disease involving the mucosal surface of the large intestine and rectum. "Furthermore, one of the autoantibodies, anti-endothelial protein C receptor, was shown to be present in ulcerative colitis (UC), which is genetically and clinically associated with TAK." (PMID 37560375, 2023).
angina (2 papers, 2024 to 2025). "In this study, we examined the distribution of the LPL rs264, PROCR rs867186 and PDGF rs974819 polymorphisms between patients with unstable angina and control subjects." (PMID 38392646, 2024). "The aim of the study was to examine the associations between the LPL rs264, PROCR rs867186 and PDGF rs974819 gene polymorphisms and the risk of unstable angina and selected clinical parameters." (PMID 38392646, 2024).
diabetic nephropathy (2 papers, 2021 to 2025). "In particular, an experimental study in mice showed that PROCR and protein C were found to ameliorate diabetic nephropathy by inhibiting hyperglycemia-induced endothelial and glomerular apoptosis." (PMID 34575035, 2021).
Takayasu arteritis (2 papers, 2025 to 2026). A rare inflammatory large-vessel vasculitis primarily affecting the aorta and its major branches, but also other large vessels, causing stenosis, occlusion, or aneurysm. "We recently identified anti-endothelial protein C receptor antibodies (anti-EPCRs) in Takayasu arteritis and showed that anti-EPCR were also associated with UC; they had pathogenic effects owing to their promotion of Th17 differentiation and endothelial activation." (PMID 40372451, 2025).
Thromboembolism (2 papers, 2014 to 2022). The formation of a blood clot inside a blood vessel that subsequently travels through the blood stream from the site where it formed to another location in the body, generally leading to vascular occlusion at the distant site. "We aimed to investigate the levels of soluble endothelial protein C receptor (sEPCR) in myeloproliferative diseases to see whether there was a difference between the patients with and without history of thromboembolism." (PMID 25035668, 2014).
thrombotic microangiopathy (2 papers, 2024 to 2025). The syndromes of microangiopathic hemolytic anemia, thrombocytopenia, and variable signs of organ impairment, due to platelet aggregation in the microcirculation. "Moreover, in earlier attempts to alleviate molecular incompatibilities in the coagulation cascade, transgenic expression of thrombomodulin (TBM), endothelial protein C receptor (EPCR), and CD47 minimized the thrombotic microangiopathy (TMA) that led to early graft failure." (PMID 41451219, 2025).
acute coronary syndrome (1 paper, 2025). Signs and symptoms related to acute ischemia of the myocardium secondary to coronary artery disease. "Fluvastatin, when administered within 6 h of acute coronary syndrome, reduces soluble endothelial protein C receptor (sEPCR), thereby decreasing thrombin activation." (PMID 41375704, 2025).
falciparum malaria (1 paper, 2015). "This study investigated the four defined EPCR haplotypes resulting from SNPs of the PROCR gene and their possible association with the level of sEPCR and disease outcome in Tanzanian patients infected with falciparum malaria." (PMID 26620701, 2015).
glioma (1 paper, 2024). A benign or malignant brain and spinal cord tumor that arises from glial cells (astrocytes, oligodendrocytes, ependymal cells). "Therefore, we evaluated the presence and specific localization of aPC and its receptor endothelial protein C receptor (EPCR) in C6 glioma cells during mitosis stages by immunofluorescence." (PMID 39027436, 2024).
heart failure (1 paper, 2017). Inability of the heart to pump blood at an adequate rate to meet tissue metabolic requirements. "Some primary mechanisms include: 1) Impairment of the protein C pathway, specifically, the endothelial protein C receptor (EPCR) is down regulated through inflammatory cytokines elevated in patients with heart failure, which impairs the protein C pathway-mediated anticoagulation." (PMID 28450810, 2017).
Insulin resistance (1 paper, 2019). Increased resistance towards insulin, that is, diminished effectiveness of insulin in reducing blood glucose levels. "protein C receptor, endothelial (EPCR) (PROCR), C1R, CFI, PLAT, C4BPB, and CFB are novel biomarkers for the development of insulin resistance." (PMID 30678306, 2019).
invasive ductal carcinoma of the breast (1 paper, 2019). "EPCR (PROCR, protein C receptor, CD201) expression was also assessed in invasive ductal carcinoma of the breast from 271 patients with stage II or III disease." (PMID 30626007, 2019).
mesenchymal tumors (1 paper, 2021). "LMS4 showed marked expression of absorptive enterocyte markers, and LMS5-mesenchymal tumors showed strong expression of markers of quiescent stem cells (DLCK1+, PROCR+)." (PMID 34470666, 2021).
metastatic carcinoma (1 paper, 2016). A carcinoma which has spread from the original site of growth to another anatomic site. "A recent investigation describes the tumor-initiating properties of PROCR detected in cancer stem-like cells in the context of aggressive invasive/metastatic carcinomas, and this is the first report showing the upregulation of PROCR on the surface of cells expressing oncogenic KRasG12V." (PMID 27894102, 2016).
retinal vein occlusion (1 paper, 2017). An occlusion of the retinal vein. "There is one study suggesting that high levels of soluble endothelial protein C receptor (sEPCR) might be a risk factor for retinal vein occlusion (RVO) because the levels were higher in patients with CRVO than in those with branch retinal vein occlusion (BRVO) and controls." (PMID 28302155, 2017).
serous ovarian cancer (1 paper, 2022). "Accordingly, overexpression of some acting on genes like FOSL2, NFIB, NFIC, and PROCR, which are associated with proliferation and metastasis, predicts poor prognosis in high-grade serous ovarian cancer." (PMID 35935940, 2022).
Streptococcus pneumoniae infection (1 paper, 2024). "For example, Streptococcus pneumoniae infection is associated with lung vascular dysfunction in mice by impairing lung compliance via overexpression and function of Endothelial Protein C Receptor (EPCR)." (PMID 39406383, 2024).
tonsillitis (1 paper, 2024). Inflammation of the tonsillar tissue. "Furthermore, complement and coagulation cascades, including MBL2, TFPI, and PROCR have been identified as biomarkers related to phenotypes such as tonsillitis." (PMID 39410993, 2024).